APOE (apolipoprotein E)
Diseases named in the same sentence as APOE in open-access papers (continued):
Sharing a sentence is not in itself a finding about the gene and the disease.
dementia (continued). "Increased risk for developing dementia was seen for those carrying at least 1 APOE ε4 allele (5-fold increase compared with 2 APOE ε3 alleles), having 2 or more comorbid health conditions (2-fold increase), and having early-onset epilepsy (near 4-fold increase)." (PMID 30452522, 2019). "In line with the hypothesis that low IGF-I activity increases the risk of dementia, we found the ApoE-ε4 homozygotes, with a lifetime risk of AD of 80%, have the lowest IGF-I levels." (PMID 30809143, 2019). "We accounted for numerous potentially confounding lifestyle variables which have been found to be associated with serum 25(OH) D concentrations and increased risk of dementia such as increasing age, black race, physical activity etc. as well as for the APOE ε4 genotype." (PMID 31640594, 2019). "Given the previously reported association between ApoE and cognitive function in the elderly, we hypothesize that ApoE gene polymorphism might interact with steroid hormones in affecting cognitive performance in non-dementia elderly Chinese." (PMID 29559956, 2018). "One of the strongest risk factors for dementia is the ε4 variant of the APOE gene." (PMID 29414991, 2018). "Studies have shown that APOE ε4 increases the risk of dementia." (PMID 30519639, 2018). "The current study examined for the first time whether positive age beliefs that are acquired from the culture may reduce the risk of developing dementia among older individuals, including those who are APOE ε4 carriers." (PMID 29414991, 2018). "After adjusting for older age, lower education, lower MMSE score, higher WHODAS II score, lower physical activity, and presence of the APOE e4 allele, the incidence of dementia increased significantly with increases in the summed number of changes to higher cytokine levels at follow-up." (PMID 30510525, 2018). "In addition, our research was conducted in African Americans, an under-studied population with high prevalence of dementia and high allele frequency of APOE ε4." (PMID 29739406, 2018). "This indicates that while AF itself might not be enough to cause clinical dementia, the coexistence of AD pathology associated with APOE ε4 allele and cerebrovascular lesions related to AF could lead to a substantial risk of dementia than either process alone." (PMID 30305443, 2018). "Among participants with dementia (n = 5), 4 had the APOE ε4 allele (p = 0.017)." (PMID 29653987, 2018). "With widely recognised risk factors for dementia – such as age and APOE ε4 allele status – being fixed and unchangeable, identifying potentially modifiable risk factors would be of considerable value in contributing to the development of strategies aimed at reducing disease incidence." (PMID 30180830, 2018). "Moreover, as reported in previous population studies on cognitive impairment or dementia, while the APOE ε4 allele has been associated with various cognitive domains, the strongest association was observed for memory." (PMID 29739406, 2018). "Moreover, among those with APOE ε4, there was a 49.8% lower risk of dementia for those holding positive age beliefs at baseline, compared to those holding negative age beliefs at baseline." (PMID 29414991, 2018). "It has also been highlighted that diet may interact with genetic risk factors for dementia, namely the Apolipoprotein E4 (APOE ε4) allele, which is important to take into consideration when investigating the associations between diet and dementia." (PMID 30400288, 2018). "Future studies are needed to clarify whether and how RNF219/G plays in synergy with the gender and APOE-ε4 status to affect the neurodegenerative processes underlying dementia." (PMID 29755337, 2018). "Besides other risk factors, apolipoprotein E (ApoE) gene polymorphism has been implicated in predisposition to diabetes and dementia in old population, but the results from the different studies were inconclusive." (PMID 30049934, 2018).
dementia (continued). "With regard to genetics, the Apolipoprotein E (APOE) genotype, a major risk factor for AD in younger subjects, has been extensively studied in the oldest-old, with mixed results regarding the relation to cognition and dementia." (PMID 30477432, 2018). "The presence of an APOE ε4 allele, smoking, lower physical fitness, and lower vitamin B-12 were all associated with greater relative cognitive decline between age 11 and 79 years even after excluding those who had developed dementia in the next 16 years." (PMID 29745686, 2018). "Future studies could investigate whether individuals presenting additional risk factors for future dementia (e.g., family history of AD, APOE ε4 carriers) would respond differently to an exercise intervention similar to what presented in the current study." (PMID 29698440, 2018). "The APOE ε4 allele has been associated with a higher prevalence of dementia in PD." (PMID 29692703, 2018). "Using χ2 analyses, we tested whether the association between ApoE genotype and chronic low-grade inflammation status with the risk for incident dementia including AD and mortality changed when using different CRP cutoff levels." (PMID 30646251, 2018). "These analyses showed that, beyond age and APOE-e4, the following variables were associated with increased risk: less education, memory concerns or poorer cognitive screening test scores at the beginning of follow-up, and having a family history of dementia." (PMID 28323826, 2017). "In regression models, APOE-e4 dose and age both consistently increased risk, as did lower education, subjective memory concerns, poorer baseline cognitive performance, and family history of dementia." (PMID 28323826, 2017). "The APOE e4 allele has been linked to poorer cognitive aging and enhanced dementia risk." (PMID 28239522, 2017). "As expected, individuals who would develop dementia later were relatively older, more likely to be female, had more depressive symptoms, reported poorer cognitive functioning, and were more likely to be APOE ε4 allele carriers." (PMID 28291786, 2017). "We also tested whether the phosphorylated (active) forms of these proteins were associated with (i) dementia status; (ii) cognitive impairment; (iii) specific features of AD pathology and (iv) APOE genotype." (PMID 27106634, 2017). "Stratified analysis according to APOE ɛ4 status furthermore revealed that having high cognitive reserve in two or three periods over the life course was associated with a lower risk of dementia in both ɛ4 allele carriers (RR 0.5; 95% CI 0.3–0.9) and ɛ4 allele noncarriers (RR 0.7; 95% CI 0.5–0.97)." (PMID 28291786, 2017). "We hypothesized that long-term PM2.5 exposure increases the risk for accelerated global cognitive decline and dementia, further exacerbated by APOE ɛ4." (PMID 28140404, 2017). "An earlier study evaluating the role of ApoE in dementia associated with PD was inconclusive." (PMID 29326545, 2017). "Overall, within each cohort, risk of MCI/dementia increased with increasing age and APOE-e4 dose." (PMID 28323826, 2017). "Overall, the estimates for APOE-associated risk of MCI or dementia were lower in our study than previously reported, and there is reason to believe that the risk estimates obtained in the population-based cohorts more accurately reflect the general population than those obtained in NACC." (PMID 28323826, 2017). "APOE ε4 has been associated with accumulation of amyloid and/or tau pathology in AD but the relationship with post-stroke dementia has been conflicting and less well defined." (PMID 29311794, 2017). "This may be the first demonstration of any serum protein’s mediation effect on the APOE ε4 allele’s association with either dementia, or with observed cognitive performance." (PMID 28291794, 2017). "The risk of dementia in those with APOE-e4/e4 is somewhat lower than previously estimated." (PMID 28323826, 2017).
dementia (continued). "There was substantially higher risk of MCI/dementia with increasing age (HR 1.08–1.16 per year of age), increasing APOE-e4 dose (for one copy, HR 1.51–2.23; for two copies, HR 2.63–3.57), and lower education (HR 1.41–1.86 for less than high school compared to high school)." (PMID 28323826, 2017). "One could argue that previously available modeled estimates for APOE-e4-associated absolute risk for dementia are high (50%–67%), and thus favor the NACC estimates instead." (PMID 28323826, 2017). "As APOE is the major genetic risk factor for dementia of the Alzheimer type, our results strengthen the notion that odor identification might be a marker of pre-clinical dementia in middle age." (PMID 28455505, 2017). "Second, the observed associations may be an indirect marker of the relation between dementia and the APOEε4 allele, as APOE is both a key player in lipid metabolism and one of the strongest risk factors for dementia and AD (APOEε4 allele)." (PMID 28350817, 2017). "The present findings suggest that apoE fragmentation is present within the DS brain and could provide a rationale as to the enhanced dementia risk associated with the APOE4 allele in DS." (PMID 27330841, 2016). "Outside of acute illness, dementia, the APOE e4 allele, and overall physical fitness, healthy cognitive ageing is likely either to involve factors not studied here, or to be—by analogy with the ‘polygenic’ model of the genetics of complex traits —a multivariate accumulation of small influences." (PMID 27932854, 2016). "This raises the question of whether association between APOE genotype and dementia in PD reflects the development of Alzheimer’s type pathology in the aging brain." (PMID 27242557, 2016). "Longitudinal studies controlling for risk factors such as lipids, hypertension, diabetes, obesity, history of stroke, depression, smoking, educational level, APOE status, and so on generally confirm the importance of physical activity in reducing dementia risk." (PMID 27481112, 2016). "This could explain 1) the weakened association between APOE and dementia in centenarians, despite dementia's increasing incidence, and 2) the reduced burden of neurodegenerative lesions among the oldest “AD” cases." (PMID 26930722, 2016). "The allele frequency of APOE ε4 varies both across and within populations, and the size of the effect it confers for dementia risk may be affected by other factors." (PMID 25738563, 2015). "An alternative–and perhaps more intriguing–hypothesis is that Chinese APOE ε4 carriers are resistant to the risk for dementia conferred by the ε4 allele based on the presence of modifying factors specific to this population." (PMID 25738563, 2015). "In addition, and perhaps most importantly, use of CCBs mitigated the accelerated decline to dementia associated with the presence of the APOE-4 allele." (PMID 26221415, 2015). "Model 3 demonstrated that, after adjusted for sex, age, education year, living alone, BMI, cigarette smoking, alcohol drinking, anxiety, depression, heart disease, hypertension, diabetes, and APOE-ε4, tooth loss of >16 were significantly associated with dementia with an OR of 1.56 (95%CI 1.12–2.18)." (PMID 25803052, 2015). "After adjusted for sex, age, education year, living alone, body mass index, cigarette smoking, alcohol drinking, anxiety, depression, heart disease, hypertension, diabetes, and APOE-ε4, tooth loss of >16 were significantly associated with dementia with an OR of 1.56 (95%CI 1.12-2.18)." (PMID 25803052, 2015). "Fourth, the potential dose–response pattern on smoking-dementia association and the modification effect of apolipoprotein E (APOE) ε4 allele on this association remain unclear." (PMID 25763939, 2015). "Obvious polymorphic targets in dementia could include apolipoprotein E (APOE) and microtubule-associated protein τ (MAPT), given their known association with AD and α-synuclein related disorders." (PMID 25478032, 2014).
dementia (continued). "In the diagnosis of dyslipidemia and risk assessment of dementia, ApoE typing is important." (PMID 24454848, 2014). "Apart from APOE, effect sizes for individual alleles are generally small, but when combined into a polygenic risk score, these loci may have large joint effects on dementia risk." (PMID 25328845, 2014). "Knowing the ApoE genotype of a person with a neurodegenerative disease might therefore give insight on the risk of developing dementia." (PMID 25071563, 2014). "It is clear, however, that individuals with the APOE-ε4 genotype are at high risk for AD type dementia, and may represent an ideal target for interventions." (PMID 25538616, 2014). "As in AD, the genetic risk posed by apolipoprotein E ε4 (APOE ε4) may play a role in the dementia associated with CTE." (PMID 25231386, 2014). "Our previous report suggested PICALM and APOE as risk factors for early onset of dementia in DS." (PMID 24462566, 2014). "At present, the absence of COMT from the pantheon of MCI-related genes may be associated with the fact that, by the time individuals convert to dementia, the genetic associations are overwhelmed by APOE and its direct connection to amyloid beta deposition." (PMID 25249975, 2014). "Additionally, some European studies have suggested that the effect of the APOE ε4 allele on dementia and mortality disappears in very old age." (PMID 25085564, 2014). "A plausible hypothesis for apparent age dependent relationship between serum cholesterol and dementia is that there are distinct differences in serum cholesterol levels from midlife through late life according to APOE allele status." (PMID 25325355, 2014). "The ε4 allele of APOE is associated with earlier age at onset and increased risk of AD whilst the APOE ε2 allele may reduce the risk of dementia in heterozygous carriers." (PMID 24438528, 2014). "However, the association between APOE genotype and incident dementia was, incomparison, greatly attenuated." (PMID 29213926, 2014). "The aim of the present study was to investigate if ApoE genotypes are associated with BBB function (estimated by cerebrospinal fluid-serum albumin ratio) in a large cohort of patients with different types of dementia." (PMID 24386372, 2013). "Although the effects of apoE may alter susceptibility to environmental factors such as stress, further studies are required investigate the mechanism of how occlusal disharmony appears to modulate the effects of apoE deficiency on dementia." (PMID 24066161, 2013). "In the present study we addressed the question if ApoE genotypes might be associated with BBB function measured by albumin ratio (QAlb) in a large cohort of patients with different types of dementia." (PMID 24386372, 2013). "Carriers of the APOE ε4 allele are at an increased risk of dementia, whereas carriers of the APOE ε2 allele might be protected." (PMID 23483953, 2013). "Given the discrepancy between this finding and those in two published studies, the relationship between the number of APOE ε 4 alleles and plasma APOE levels was studied in an independent cohort of 694 subjects (AddNeuroMed and King's Health Partners Dementia Case Register, ANM + KNPDCR)." (PMID 23028511, 2012). "The APOE-4, a major genetic risk factor for sporadic AD, has been found to affect gray matter and white matter structure as well as cortical rhythms and functional/structural connectivity in healthy subjects long before the onset of clinical dementia." (PMID 23050006, 2012). "Consistent with the rodent literature, several epidemiological studies have also reported that the association between greater amounts of physical activity and reduced risk of dementia might be dependent on APOE genotype." (PMID 23304508, 2012). "Data from the first dementia study that is representative of the USA population suggest that antihypertensive medications may be neuroprotective, whereas stroke and APOE ε4 are strongly associated with dementia." (PMID 20576093, 2010).
dementia (continued). "We therefore stratified the association between stroke and dementia by APOE ε4 genotype." (PMID 20576093, 2010). "Carriers of the apolipoprotein E (APOE) ε4 allele, a genetic modifier, are at increased risk for the development of sporadic AD, manifest dementia symptoms earlier than ε4-negative persons with the disease, and exhibit accelerated conversion rates from MCI to AD." (PMID 20811568, 2010). "Although some studies suggest that the association between vascular conditions and dementia may be modified by APOE ε4, we only observed a significant interaction with stroke." (PMID 20576093, 2010). "An important question to address is whether APOE *E4 carrier status is associated with more rapid cognitive decline in the general population when those with either dementia or preclinical dementia are excluded." (PMID 18620605, 2008). "Additionally, high eGDR may attenuate the APOE ε4 genetic risk of dementia and brain aging among diabetes-free people." (PMID 41181882, 2026). "Interaction terms were tested to evaluate whether sex, age, race, education, depression, diagnostic form, referral source, the primary reason to visit ADRC, and APOE ε4 moderated the associations between marital status (unmarried vs. married) and risk of dementia." (PMID 40110684, 2025). "However, whether the association between CMP and dementia is modified by the APOE genotype, the strongest genetic risk factor for dementia, remains unclear." (PMID 40101131, 2025). "Moreover, it remains unclear whether APOE-associated dementia risk is shaped or suppressed by the social environments in which individuals age." (PMID 41264567, 2025). "Whether APOE E4 carrier status poses a similar risk of dementia in LRRK2 and/or GBA1 PD is unknown." (PMID 40926580, 2025). "ApoE may have an association with midlife vascular mortality in males that could contribute to the observed sex differences in associations between ApoE and dementia in late life." (PMID 41109864, 2025). "Moreover, utilizing APOE-genotypes as a prescreening tool for future research is well-accepted by cognitively healthy volunteers, supported by the positive responses on survey on information provision, understanding of genetic dementia risk and project scope." (PMID 40000321, 2025). "Plasma NfL accounted for 7.3% of the total association between ILF and dementia (p = 0.01), while serum p-Tau181 mediated 4.9% of the association (p = 0.05; figure not shown) after accounting for baseline age, sex, race, BMI, smoking status, education, comorbidity index and APOE e4." (PMID 41502564, 2025). "Beyond the well-documented role of apoE, genetic variability in Human Leukocyte Antigen (HLA)—which plays a crucial role in immune response—may influence individual susceptibility to infection and the corresponding impact on dementia biomarkers." (PMID 40664837, 2025). "Interestingly, among APOE-ε4 carriers, only having less than upper secondary education was associated with greater dementia risk, whereas dementia risk remained elevated across all income levels (intermediate and low) when compared to those with high family income." (PMID 41264567, 2025). "Additive interaction was evaluated by estimating the relative excess risk due to interaction (RERI), the attributable proportion (AP), and the synergy index (SI), indicating whether the combined effect of CMP and APOE ɛ4 on dementia risk is greater than expected based on their individual effects." (PMID 40101131, 2025). "As commented upon, this connection between APOE E2 and biological oldness seems contradictory, with APOE E2 generally predicting longevity and being protective against AD, whereas insulin resistance and diabetes as suggested here are risk factors for dementia and accelerated aging." (PMID 40323280, 2025).